CD4 (CD4 molecule)
Diseases named in the same sentence as CD4 in open-access papers (continued):
Sharing a sentence is not in itself a finding about the gene and the disease.
infection (continued). "Here we show the increase in specific T-cell response, which agrees with the later paper that showed an increase in CD4+TNF-α+ cells in animals immunized with rBCG-LTAK63, fifteen days after H37Rv infection." (PMID 37520577, 2023). "The level of infection after IEC stimulation was more substantial in memory CD4 + T cells than naïve CD4 + T cells, correlated with the in vivo observation that memory CD4 + T cells harbor much more HIV infection than naïve CD4 + T cells." (PMID 37202790, 2023). "For instance, the presence of specific subsets of CD4+ and CD8+ T cells for internal proteins of Influenza virus showed an evident correlation with better outcomes for this infection." (PMID 36767315, 2023). "H3N2-specific CD4+ T cells were predominantly IL-2 single producers, and this response was maintained over the course of H3N2 single infection (mean of 0.10%, 0.06%, and 0.09% at 14, 28, and 34 dpi, respectively)." (PMID 37287962, 2023). "Similar to our findings in μMT mice, by two weeks post infection co-transfer of B cells enhanced FoxP3 expression and diminished T-bet expression on CD44+CD4+ T cells." (PMID 37721965, 2023). "For protection from secondary infection, in contrast, there is a greater role for MHC class II-restricted CD4 T cells as well as MHC II-restricted but CD4-independent mechanisms." (PMID 37885896, 2023). "Intestinal immune responses, namely HRV-specific IgA and IFN-γ producing CD4+ and CD8+ T cells induced by vaccination or natural infection are extremely important in the protection from clinical signs of subsequent HRV infection." (PMID 37243031, 2023). "In comparison to natural infection, patients who received the JYNNEOS vaccine showed equivalent CD4 and CD8 T cell responses to orthopox peptides." (PMID 38006040, 2023). "Our intervention prolonged T cell activation for over 100 days of infection, well beyond the transition from acute to chronic stage of SIV infection, maintaining an increased viral replication and delaying the postacute CD4+ T cell restoration." (PMID 37485874, 2023). "On the other hand, type I IFN signaling on NK cells was shown to be crucial for killing CD4+ and CD8+ T cells during LCMV Cl 13 infection." (PMID 37766322, 2023). "These long-lived cells are able to proliferate homeostatically, i.e., in the absence of antigenic stimulation, providing “ad aeternum” persistence of the infection, as evidenced by the presence of HIV-infected CD4+ T-cell clones of about 18 years old." (PMID 37569570, 2023). "After adoptive transfer of CD4+ T cells, the levels of IgG, IgM, IgA and IgE in serum of rEg.P29+CpG+Infection were significantly increased compared with those of the CD4+T+PBS+Infection and CD4+T+CpG+Infection group." (PMID 38151996, 2023). "To better understand the biological pathways modulated by the infection in B, CD14+, CD4+ and CD8+ cells, we next performed an over-representation analysis (ORA) using the Kyoto Encyclopedia of Genes and Genomes (KEGG)." (PMID 37920474, 2023). "The pulmonary CD4+ T cells of C. neoformans-infected mice showed a predominant co-expression of IL-17RB and ST2, particularly at the late infection stage." (PMID 37337050, 2023). "Next, correlation analyses were performed between T-cell activation and CD4 counts in PLWH before and after breakthrough infection." (PMID 38140668, 2023). "A specific subpopulation of CD4+ T cells with type I interferon production potential (IFN-act TN) was increased in PBMCs and spleens after infection with E. granulosus." (PMID 37039643, 2023). "However, at later stages during TiLV infection (at 6 to 14 days post-infection), a significant up-regulation of the expression of CD4 markers cd4-1 and cd4-2 was observed in the liver and spleen of TiLV-infected zebrafish, suggesting the activation of CD4+ and their cell-mediated antiviral action." (PMID 37622112, 2023). "An early study pointed to the virus-specific CD4+TSCM and CD8+ TSCM cell response during primary ex vivo infection." (PMID 38213479, 2023).
infection (continued). "Compared to CD4+ T cells, macrophages are more resistant to HIV cytopathic effects and survive longer with the infection; thus, they have an increased likelihood of interacting with and infecting uninfected cells." (PMID 37408185, 2023). "After one day of co-culturing, CD4 + T cells were infected with a GFP reporter virus, and infection rates (% GFP+) were examined on day 6 post-infection." (PMID 37202790, 2023). "It thus appears that B, CD14+, CD4+, and CD8+ cells are capable of sensing the infection and, as a consequence, trigger the transcription of IFN-related genes." (PMID 37920474, 2023). "This translates to 3.71×106 and 3.55×106 PbA-specific CD4 T cells at 6.5 and 7 days post-infection, and 6.38×106 and 1.35×107 PbA-specific CD8 T cells at 6.5 and 7 days post-infection." (PMID 37811200, 2023). "FACS analysis also showed that PD-1 MFI was significantly up-regulated on CD4+ and CD8+ T cells of infected mice in comparison with uninfected controls, showing a progressive increase throughout the infection time." (PMID 37691941, 2023). "Half of these cells are CD69+, indicating that activated T cells migrate to the site of infection, interact with M.tb-infected macrophages and DCs through CD40L on CD4+ T cells and CD40 on macrophages or dendritic cells." (PMID 37415827, 2023). "This reduction was accompanied by a diminished immune response to infection, as indicated by the lowered levels of TNF-α, IL-6, and IL-10 and altered CD4+/CD8+ T-cell ratio." (PMID 38139181, 2023). "Meanwhile, both α4β1+ CD4 Th1 and α4β1+ CCR5+ Th1 cells were significantly reduced during acute infection in both the brain and spleen." (PMID 38060615, 2023). "By using additional flow cytometry in our study, we found spike-responsive CD4+ T cell frequencies to increase mainly after vaccination and spike-responsive CD8+ T cell frequencies to increase by infection." (PMID 38193077, 2023). "HIV models have been established recently to understand the behaviour of the virus after infection, HIV disease dynamics, the immune response, and the interactions of the virus with CD4 + T cells." (PMID 37156899, 2023). "For CRF07_BC, both baseline CD4+ T cell count (p = 0.0270) and baseline CD4+ T/CD8+ T ratio (p = 0.0090) were lower in the X4-tropic infection." (PMID 37152735, 2023). "Specific CD4+ and CD8+ T cells were induced strongly early post infection in the mild group, moderately, but increased gradually, in the severe group, substantially and rapidly in NA cases, and weakly in PA cases from beginning to end." (PMID 36922500, 2023). "Peripheral blood CD3+CD4+ and CD3+CD8+ were exposed to mock control or SARS-CoV-2 (CoV-2) (Multiplicity of Infection (MOI) = 1) for 1 hr under continuous agitation." (PMID 37523305, 2023). "Initially, we carried out a phenotypic and functional analysis of CD4+T and CD8+T cells that stimulated a response in the context of vaccines against infection." (PMID 38213479, 2023). "Persistent S. Enteritidis and S. Heidelberg infections were reported in chickens by the induction of CD4+CD25+ cells and by the variation in IL-10 mRNA transcription, resulting in an asymptomatic carrier state in birds 18 days after infection." (PMID 38004824, 2023). "Activation of S-specific CD4+ and CD8+ cells were detected during the first week of infection, together with an expansion of S-specific plasmablasts." (PMID 38005881, 2023). "We found that most IL-17RB+ CD4+ T cells were co-expressed with ST2, particularly at the late phase of infection." (PMID 37337050, 2023). "Infection of HEK293T and transformed human CD4+ T cells expressing C-C chemokine receptor 5 (HuT/CCR5) was confirmed by immunoblotting for Gag p55 or via luciferase assays with infected cell lysates." (PMID 36851687, 2023). "In the FV model we also observed both FasL-mediated and exocytosis-mediated killing by CD4+ CTL, which was regulated by virus dose, infection phase, and application of immunotherapies." (PMID 37965314, 2023).
infection (continued). "Analysis of CD4 and CD8 T cell populations also revealed a reduction in their percentage values after infection in both BALB/c and C57BL/6 mice." (PMID 37511092, 2023). "Deletion of Bcl6 in CD4+ T cells and CD40L blockade both thwart development of GC responses in Brucella infected mice yet have opposing effects on control of infection." (PMID 37721965, 2023). "On the other hand, the frequencies of CXCR5+TIM-3+ cells within both CD4+ and CD8+ T cells reached comparable values at 30 (2-4%) and 60 (7-10%) days after infection." (PMID 37691941, 2023). "By recognition of different gammaherpesvirus-infected cell types, CD4+ and CD8+ T cells can cooperate to control the infection." (PMID 37065193, 2023). "On the other hand, in individuals with a history of infection, the proportion of TEM among SARS-CoV-2-specific CD4+ T cells tended to increase upon vaccination, and this increment was statistically significant for S Wuhan-specific cells (p-value=0.03)." (PMID 37575243, 2023). "We demonstrate evidence to support a role for CD4+ and CD8+ T cells as well as antibodies against Delta vaccine breakthrough infection." (PMID 37655880, 2023). "The frequencies of CD4+ RhCMV–specific T cell responses were reduced relative to parental 68-1 and UCD59 infections but remained stable over time." (PMID 36749635, 2023). "We observed that at 7 days post-infection, there was a significant expansion of IL-17A+ cells, including TH17 (CD45+, CD3ε+, CD4+, GFP+) cells." (PMID 37923768, 2023). "We detected the proportion of CD4+ T, CD8+ T, and NK cells in the blood, lungs, and spleen of mice using flow cytometry before and after infection." (PMID 37953509, 2023). "Additionally, since the cell-free system obviates the need for identifying the nature of the APC, it is unclear whether infected CD4+ T cells present these peptides directly or whether DCs indirectly present these epitopes during the course of natural infection." (PMID 37058141, 2023). "Similar findings have been observed in mouse models of IAV infection demonstrating that IFNγ+ CD4 and CD8 T cells can protect mice from challenge infection." (PMID 37842651, 2023). "We also detected some MCMV-specific CD4 T cell responses using MCMV m78 tetramer at 11 and 60 days after MCMV-B5 infection." (PMID 37205446, 2023). "Regarding the T cell-mediated immunity, SARS-CoV-2-specific CD4+ and CD8+ T cells induced by both vaccination and infection in healthy individuals have been shown to be cross-reactive against VOC, including Omicron." (PMID 36839516, 2023). "Mice infection with Theiler’s murine encephalomyelitis virus (TMEV), showed persistent infection of microglial cells and CD4+-T-cells-mediated immune response to myelin epitopes presented by microglial cells, resulting in autoimmune demyelinating disease." (PMID 36937670, 2023). "In this study, we investigated the differences in Ag-specific CD4 and CD8 T cell immunity from mice infected with different doses of infection." (PMID 36883950, 2023). "Overall, transcriptomic analysis of B, CD14+, CD4+ and CD8+ cells indicates that BTV infection starts altering the activity of these immune cells early in the infection (by day 3pi)." (PMID 37920474, 2023). "In human experimental infection studies, numbers of RSV F- and G-specific, CD4+ T cells were increased in the airways of infected individuals." (PMID 37896776, 2023). "The envelope (Env) glycoprotein of human immunodeficiency virus type-1 (HIV-1) is the virus attachment protein that interacts with the host-cell receptor CD4 and chemokine receptors CCR5 or CXCR4 to initiate infection." (PMID 37681958, 2023). "The dynamics and interaction between CD4+CD25+ and co-stimulatory molecules such as CD28, CD80, CD40 and CD40LG during infection with A. phagocytophilum in sheep needs further investigation in the future." (PMID 37989861, 2023).
infection (continued). "Influenza-virus-specific CD4+TRMs in mice were shown to produce IL-2 and IFN-γ in the lungs upon infection and protect mice from lethal H1N1 virus challenge." (PMID 36851616, 2023). "From 2011 to 2016, people living with HIV began ART when their CD4 count was ≤350 cells/mm3, or when they presented with serious HIV clinical infection (WHO clinical stage 3 or 4)." (PMID 36828530, 2023). "Our results suggest therefore that Spike-reactive CD4 + and CD8 + T cells cross-recognize delta and omicron VOC 6 months after infection in unvaccinated children with equal avidity." (PMID 37993788, 2023). "We infected the purified CD4+ cells from TCR stimulated HTOC, infected with HIV-1 in the presence or absence of inhibitors, and treated them with ARI, 24–36 h post-infection." (PMID 36693889, 2023). "The change in CD3+ lymphocytes is, in part, reflected by the increase in number of CD4+ and CD8+ T cells throughout infection." (PMID 37112973, 2023). "Before that, from 2011, teenagers and adults only began ART when they presented with a serious or progressed HIV clinical infection (WHO clinical stage 3 or 4), or with a CD4 count ≤ 350 cells/mm3." (PMID 36828530, 2023). "CT also enhances the accumulation of CD4+ T cells that express the HIV co-receptors CXCR4 and CCR5 at the site of infection." (PMID 37766360, 2023). "T. gondii infection induces a strong CD4+ T cell response, which is the main source of IFN-γ during infection." (PMID 37077528, 2023). "During the acute phase, we demonstrate that the lower dose of infection generates a reduced number of CD4 and CD8 T cells, but the frequency of functional CD4 or CD8 T cells is similar in animals infected with two different doses." (PMID 36883950, 2023). "Acute HIV infection led to a reduction of CD4+ T-cells, inversion of the CD4:CD8 ratio, and a reduction of peripheral CD56bright NK cells, which was similar to patterns found during natural human infection." (PMID 37630544, 2023). "In experiments on PBMC infection by NL4.3Balenv, the CD4/CD8 ratio was indifferent to the presence of EV-miR-155 (NL4.3BE/EV-miR-155)." (PMID 36766808, 2023). "Consistent with IFN-γ ELISpot assay results, the frequencies of IFN-γ, TNF, and IL-2 single, double, and triple producers within the CD4+ and CD8β+ T-cell subsets were overall low after H3N2 single infection (mean < 0.5%)." (PMID 37287962, 2023). "CD4+ and CD8+ T cells curtail the infection by the production of IFN-γ, tumor necrosis factor alpha, and IL-2 as well as by direct cytotoxicity or lysis of infected cells." (PMID 37903443, 2023). "In active VL, both CD4 and CD8 cells function cooperatively for clearance of infection displaying diverse functions and expression of the cytokines." (PMID 37265481, 2023). "In the present study, by utilizing AIM detection after in vitro stimulation, we revealed consistent virus-specific CD4+ and CD8+ T-cell responses over 9 months post-infection in 97% of tested donors as compared to 63% in ELISpot." (PMID 37046496, 2023). "CD4+ and CD8+ T cell responses are generated rapidly, with a delayed humoral immunity after breakthrough infection." (PMID 37887770, 2023). "Representative MFI of FAM-FLICA+ CD4+, CD8+, CD11c+, and CD14+ splenic cells in one HIV-1 infected huNSG mice treated with vehicle or with VX-765-treated mice at day 22 post-infection is shown." (PMID 36800238, 2023). "A murine model of T. gondii infection has demonstrated a synergistic role for both CD4 and CD8 T cells in controlling the infection and maintaining the chronicity." (PMID 36883950, 2023). "IPPK KO, IPMK KO, and the respective control CD4+ MT-4 cells lines were challenged with the panel of IP6-dependent HIV-1 CA mutants and assayed for single cycle infection." (PMID 37267431, 2023). "Among these patients, four had CD4+ counts below 200/μl and two of them had HIV viremia as they did not receive anti-retroviral therapy (ART) at the time of MPXV infection." (PMID 37273167, 2023).
infection (continued). "In both infection settings, the MDSC sub-population that accumulates suppresses CD4+ T cell proliferation and IFN-γ production, critical components of protective immunity to M. tuberculosis." (PMID 35757733, 2022). "Several studies in mice have shown the importance of CD4 and CD8 T cells in controlling infection with C. burnetii." (PMID 35693783, 2022). "Four days after challenge infection with H5N1 or H3N2, murine lungs were isolated and the immune responses of CD4+ and CD8+ T cells were confirmed from total cells." (PMID 35216022, 2022). "Marked infiltration of γδT cells, CD4+ and CD8+ T lymphocytes were observed in ARV infected tendon tissues starting day 3 post-infection." (PMID 35369435, 2022). "We were able to detect tissue-resident (CD103+ CD69+) CD4+ and CD8+ T cells specific for Spike and other SARS-CoV-2 proteins only in vaccinated individuals who suffered a breakthrough infection." (PMID 36142588, 2022). "Strikingly, whereas T-cell apoptosis ratios increased after infection in WT and Axl−/− mice, the percentages of late (7-AAD+AnV+ cells), but not early (7-AADnegAnV+ cells), apoptotic cells increased only in CD4 and CD8 T cells from infected Axl−/− mice." (PMID 36581764, 2022). "Baseline antigen-specific CD4+ T cell response is a predictor of the maintenance of antibody neutralization breadth and RBD-specific memory B cell levels at 12 months post-infection." (PMID 35891232, 2022). "Using fluorescence in situ hybridization, presence of HIV RNA in phenotypically resting CD4 T cells was detected also, albeit at lower levels compared to activated cells, in lymph node biopsies of people with HIV during acute and early infection." (PMID 35895672, 2022). "Frequency IFN-γ and IL2 responses to CD4+CD8 pools and S, N, and M pools in matched asymptomatic and symptomatic post-infection participants." (PMID 35390102, 2022). "Increasing studies suggest a close cross-talk of NKT with DCs in the lymphoid and non-lymphoid tissues, and this cross-talk has a significant impact on CD4 and CD8 T cell responses to infections and the outcome of infectious diseases." (PMID 35185930, 2022). "More in detail, the presence of T CD4+ and CD8+ lymphocytes has been confirmed over time in subjects recovering from SARS-CoV-2 up to 18 months after infection." (PMID 36362500, 2022). "We observed that the frequency of Vhl cKO CD4 T cells after anti-CD3/CD28 stimulation of splenocytes was low, resembling changes in T cell frequencies during infection in vivo." (PMID 36064840, 2022). "At 10 months post-infection, almost all the enrolled individuals were still positive for SARS-CoV-2-specific IFN-γ- and TNF-α-producing CD4+ T-cells against the M viral protein and for anti-S1 or anti-RBD immunoglobulins." (PMID 34967260, 2022). "On the other hand, the infiltration of immune cells into the spinal cord, increased by TMEV infection, was diminished after ORY-2001 treatment, which specifically decreased the accumulation of CD4 and CD8 lymphocytes into the parenchyma." (PMID 35890315, 2022). "Infections stimulate both CD4+ and CD8+ T cell subsets, and optimal humoral and cellular immunity is dependent upon the activation of CD4+ T helper cells, which support CD8+ T cell function but can also themselves have effector functions." (PMID 35051231, 2022). "We first analyzed major lymphocyte cell types including T (CD4 + helper T and CD8 + cytotoxic T), B, and natural killer (NK) cells for their population changes or the presence of viral antigen upon infection." (PMID 35277473, 2022). "On the other hand, a smaller number of CD4+ICOS+Foxp3+ cells and reduced amount of IL-10 were observed during the infection with P. chabaudi and P. yoelii 17XNL." (PMID 35109868, 2022). "We observed a significant increase of the number of reads mapped to the SIV genome on day 10 in total RNA extracted from CD4 T cells in LNs (P < 0.05), indicating the presence of productive SIV within CD4 T cells following infection." (PMID 36000842, 2022).